SMURF2 (SMAD specific E3 ubiquitin protein ligase 2)
Description:
E3 ubiquitin-protein ligase which accepts ubiquitin from an E2 ubiquitin-conjugating enzyme in the form of a thioester and then directly transfers the ubiquitin to targeted substrates. Interacts with SMAD7 to trigger SMAD7-mediated transforming growth factor beta/TGF-beta receptor ubiquitin-dependent degradation, thereby down-regulating TGF-beta signaling. In addition, interaction with SMAD7 activates autocatalytic degradation, which is prevented by interaction with AIMP1. Also forms a stable complex with TGF-beta receptor-mediated phosphorylated SMAD1, SMAD2 and SMAD3, and targets SMAD1 and SMAD2 for ubiquitination and proteasome-mediated degradation. SMAD2 may recruit substrates, such as SNON, for ubiquitin-dependent degradation. Negatively regulates TGFB1-induced epithelial-mesenchymal transition and myofibroblast differentiation. Acts as an activator of ferroptosis by mediating ubiquitination and degradation of GSTP1, thereby preventing detoxification of 4-hydroxynonenal (4-HNE) reactive aldehyde. Acts as a positive regulator of smoothened signaling pathway by mediating ubiquitination of PTCH1, leading to endocytosis and lysosomal degradation of PTCH1 (By similarity). (Microbial infection) In case of filoviruses Ebola/EBOV and Marburg/MARV infection, the complex formed by viral matrix protein VP40 and SMURF2 facilitates virus budding.
Tractability: Small molecule: it has a high-quality binding pocket. Antibody: UniProt places it where antibodies can reach, with high confidence; its Gene Ontology location is reachable by antibodies, with medium confidence. PROTAC: UniProt records ubiquitination sites on it; ubiquitination databases record sites on it; a small molecule that binds it is known.
Target class: Enzyme; Transferase
Gene: Protein-coding gene on chromosome 17 (64,542,282 to 64,662,335, reverse strand). Ensembl gene ENSG00000108854.
Subcellular location: Nucleus; Cytoplasm; Cell membrane; Membrane raft
Subcellular location (Human Protein Atlas): Nuclear speckles
Pathways (Reactome):
Signal Transduction: Asymmetric localization of PCP proteins; Degradation of AXIN; Downregulation of SMAD2/3:SMAD4 transcriptional activity; Downregulation of TGF-beta receptor signaling; Hedgehog 'on' state; Signaling by BMP
Gene expression (Transcription): Regulation of RUNX3 expression and activity
Immune System: Antigen processing: Ubiquitination & Proteasome degradation
Metabolism of proteins: Ub-specific processing proteases
Gene Ontology:
Molecular function: identical protein binding; protein binding; SMAD binding; ubiquitin protein ligase activity; ubiquitin-protein transferase activity
Biological process: negative regulation of MyD88-dependent toll-like receptor signaling pathway; negative regulation of transforming growth factor beta receptor signaling pathway; positive regulation of ferroptosis; positive regulation of trophoblast cell migration; proteasome-mediated ubiquitin-dependent protein catabolic process; ubiquitin-dependent protein catabolic process; lysosomal protein catabolic process; negative regulation of BMP signaling pathway; negative regulation of DNA-templated transcription; negative regulation of transcription by RNA polymerase II; positive regulation of canonical Wnt signaling pathway; positive regulation of smoothened signaling pathway; regulation of transforming growth factor beta receptor signaling pathway; Wnt signaling pathway, planar cell polarity pathway; protein ubiquitination
Cellular component: cytoplasm; membrane raft; nuclear speck; nucleus; plasma membrane; ubiquitin ligase complex; cytosol; nucleoplasm; lysosome
Genetic constraint (gnomAD): Loss-of-function variants: 26 observed, 65.93 expected, observed/expected ratio (o/e) 0.39, 90% interval 0.29 to 0.55. The upper end of that interval is the gene's LOEUF score, 0.55, which puts it in group 2 of 6, group 1 being the genes least tolerant of losing a copy. Missense variants: 436 observed, 702.12 expected, observed/expected ratio (o/e) 0.62, 90% interval 0.57 to 0.67. Synonymous variants: 219 observed, 246.81 expected, observed/expected ratio (o/e) 0.89, 90% interval 0.79 to 0.99.
Homologues: Orthologues: macaque SMURF2 (99% identical), pig SMURF2 (99% identical), dog SMURF2 (99% identical), mouse Smurf2 (99% identical), rat Smurf2 (99% identical), guinea pig SMURF2 (98% identical), tropical clawed frog smurf2 (96% identical), chimpanzee SMURF2 (96% identical), zebrafish smurf2 (93% identical), rabbit SMURF2 (92% identical), Drosophila melanogaster Smurf (64% identical). Paralogues in human: SMURF1 (76% identical), ITCH (40% identical), WWP1 (40% identical), WWP2 (39% identical), HUWE1 (39% identical), NEDD4L (38% identical), NEDD4 (37% identical), HECW1 (35% identical), HECW2 (35% identical), HACE1 (28% identical), UBE3B (23% identical), UBE3C (22% identical), and 12 more.
Diseases named in the same sentence as SMURF2 in open-access papers:
SMURF2 is named in the same sentence as 128 diseases in open-access papers, as found by Europe PMC text mining. Sharing a sentence is not in itself a finding about the gene and the disease. The quoted sentences say what the papers report.
breast carcinoma (45 papers, 2003 to 2026). "TRAF4 catalyzes K48-linked ubiquitination of SMURF2 to downregulate SMURF2 and promote breast cancer metastasis." (PMID 32357935, 2020). "In breast cancer this alteration in SMURF2 localization was also associated with the disease progression." (PMID 31003445, 2019). "Smurf2 has been found to be upregulated in several types of cancer including breast cancer and has been associated with poor prognosis in esophageal squamous cell carcinoma and renal cell carcinoma." (PMID 25191523, 2014). "Of note, histopathological evaluation of microarray data from several human cancer tissues, including breast cancer, breast invasive ductal carcinoma, and prostate cancer, indicated a reciprocal association between elevated levels of SMURF2 and reduced levels of Lamin A, and vice versa." (PMID 36918822, 2023). "However, ubiquitination of Smurf2 driven by TRAF4 in breast cancer causes Smurf2 degradation, leading to suppression of Smurf2-induced degradation of TβRI and resulting in the promotion of TGF-β cascade-induced cell migration, EMT, and invasion." (PMID 33718111, 2020). "In summary, our findings together with the low mutation rate of SMURF2 in human cancer (0.19% for prostate cancer and 0.48% for breast cancer), suggest that the main alteration in the expression of SMURF2 in prostate and breast tumors is associated with its localization." (PMID 31003445, 2019). "Notably, miR-15b family members may downregulate Smurf2 levels, a phenomenon that appears to be associated with breast cancer metastasis." (PMID 28423498, 2017). "This study aimed to evaluate the mRNA and protein levels of SMURF1 and SMURF2 in breast cancer and to elucidate their potential biological roles through in silico analyses." (PMID 41752056, 2026). "In the exploratory analysis using cancer databases the authors identified SMURF2 as more frequently amplified in tumors from young breast cancer patients when compared to elderly age groups (BRCA-TCGA)." (PMID 39208653, 2024). "In breast cancer, SMURF2 functions predominantly as a tumor suppressor, and its expression is frequently downregulated in triple-negative breast cancer (TNBC), contributing to the aggressiveness of this subtype." (PMID 39697237, 2024). "Restoration of SMURF2 levels in breast cancer cells inhibits cell proliferation and invasiveness, highlighting its therapeutic potential." (PMID 39697237, 2024). "The mRNA expression of PCP-related genes VANGL2, NOS1AP, SCRIB, WNT11 and SMURF2 in VANGL2- or NOS1AP-amplified breast cancers (most cases are co-amplified) is heterogeneous in molecular sub-types." (PMID 36675340, 2023). "TRAF4/SMURF2/HER2 complex formation was verified by co-immunoprecipitation analysis in four HER2-positive breast cancer cell lines studied and in transiently transfected HCC1954 cells and HEK293T cells." (PMID 35864174, 2022). "Then, we performed an immunofluorescence assay to identify the subcellular localizations of TRAF4/SMURF2/HER2 in HER2+ breast cancer cells." (PMID 35864174, 2022). "Further opposition comes from other investigation showing that USF2 inhibits the transcriptional activity of Smurf1 and Smurf2 to promote breast cancer cells proliferation, migration and invasion." (PMID 36319631, 2022). "Following the discovery of functional interdependence between TRAF4, SMURF2 and HER2, we subsequently evaluated the endogenous physical interaction among TRAF4/SMURF2/HER2 in HER2+ breast cancer cell lines." (PMID 35864174, 2022). "To relate our findings to the clinical settings, we examined the relationship between the protein expression of KAP1 and SMURF2 in different human normal and breast cancer tissues, using tissue microarrays (TMAs) and IHC analysis." (PMID 35406379, 2022). "Mechanistic studies showed that the SUMO E3 ligase PIAS3 maintains breast cancer organoids through Smurf2 SUMOylation under noninvasive conditions." (PMID 33968766, 2021).
breast carcinoma (continued). "Collectively, these findings identify a novel role for PIAS3-mediated Smurf2 SUMOylation in the suppression of breast cancer cell invasion." (PMID 33968766, 2021). "Similar mechanisms and actions of SMURF2 were found to be present in human breast cancer cell lines." (PMID 33418880, 2021). "Smurf2 is expressed at low levels in breast cancer, especially in TNBC, and acts as a tumor suppressor." (PMID 33968766, 2021). "Smurf2 is located in the nucleus in normal cells but exhibits significant cytoplasmic sequestration in breast cancer cells." (PMID 33968766, 2021). "Accordingly, knockdown of Smurf2 enhances Smurf1 levels, increasing breast cancer cell migration and metastasis in vivo." (PMID 33114139, 2020). "Further investigation revealed that PIAS3 potentially maintained a non-invasive phenotype through Smurf2 SUMOylation in human MDA-MB-231 breast cancer cells, indicating an anti-metastatic activity of SUMOylated Smurf2." (PMID 32733916, 2020). "In this way, Smurf2 induces ubiquitin-dependent degradation of Smurf1 and prevents migration of breast cancer cells." (PMID 33114139, 2020). "In this work, we systematically analyzed the expression levels and subcellular localization of SMURF2 in more than 660 human normal and cancer clinical samples, with primary focus on prostate and breast cancer." (PMID 31003445, 2019). "We found that while in normal cells and tissues SMURF2 has a predominantly nuclear localization, in prostate and aggressive breast carcinomas SMURF2 shows a significantly increased cytoplasmic sequestration, associated with the disease progression." (PMID 31003445, 2019). "For example, TRAF4 was shown to antagonize Smurf2 to promote metastatic breast cancer cell migration." (PMID 31076633, 2019). "The data available in the COSMIC dataset portal also indicate that Smurf2 is overexpressed in ~49% of ovarian cancer, about 18% of breast cancer, and in ~17% of soft tissue neoplasms." (PMID 30116722, 2018). "All these results suggest that Smurf2 plays a key role in regulating the tumorigenic properties of breast cancer cells in a CNKS2 dependent manner." (PMID 29534682, 2018). "SMURF2 (SMAD specific E3 ubiquitin protein ligase 2) is a tumor suppressor involved in the maintenance of genomic stability and suppression of breast cancer cells invasiveness." (PMID 29854292, 2018). "In order to further ascertain the effect of Smurf2 knockdown on the proliferative potential of breast cancer cells, we developed stable lentiviral Smurf2 short hairpin RNA (shRNA) knockdown clones in MDA-MB-231 cell line." (PMID 29534682, 2018). "SMURF2 silencing in human breast cancer cells results in a low tumorigenicity of the cells in vitro, and also, arrests cells in G0/G1 phase of cell cycle." (PMID 30619734, 2018). "For example, Zhang's group demonstrated that elevated levels of Smurf2 were required for and promoted migration, invasion and in vivo metastatic dissemination of human breast carcinoma MDA-MB-231 cells." (PMID 30116722, 2018). "We reported previously that transient inhibition of Smurf2 expression decreased the proliferative potential of breast cancer cells by modulating CNKSR2 mediated PI3K-AKT signaling csascade." (PMID 29534682, 2018). "In this article, it was disclosed that, while SMURF2 knockdown lowers aggressiveness and motility of breast cancer cells, its overexpression promotes metastasis in vivo and in vitro." (PMID 30619734, 2018). "This pro-proliferative and pro-oncogenic effect of SMURF1 in breast cancer was found to be the case with SMURF2 too." (PMID 30619734, 2018). "In a recent study, it was found that PIAS3 acts at least in part via SUMOylation of Smurf2 to suppress the invasive growth of breast cancer cell-derived organoids suggesting a potential anti-metastatic activity of SUMOylated-Smurf2." (PMID 30096838, 2018). "Our findings illuminate the roles and mechanisms of Smurf2 in the control of breast cancer pathogenesis." (PMID 28423498, 2017).
breast carcinoma (continued). "In mechanistic studies, PIAS3 maintains breast cancer organoids in a non-invasive state via sumoylation of Smurf2." (PMID 28423498, 2017). "In future studies, it will be important to determine the role of Smurf2 sumoylation in breast cancer metastasis in animal models." (PMID 28423498, 2017). "Consistent with our findings, Smurf2 knockout mice show spontaneous tumor formation including in mammary glands, suggesting a tumor suppressor role for Smurf2 in breast cancer." (PMID 28423498, 2017). "In this study, we have uncovered an important role for sumoylation in the ability of the ubiquitin E3 ligase Smurf2 to suppress the invasive behavior of breast cancer cell-derived organoids." (PMID 28423498, 2017). "Mechanistically, our data suggest that PIAS3 acts via sumoylation of Smurf2 to suppress the invasive growth of breast cancer cells." (PMID 28423498, 2017). "Collectively, these findings suggest that Smurf2 inhibits invasiveness and deformation of three-dimensional-breast cancer cell-derived multicellular structures." (PMID 28423498, 2017). "Here, we report that the E3 ubiquitin ligase Smurf2 acts in a sumoylation-dependent manner to suppress the invasive behavior of MDA-MB-231 human breast cancer cell-derived organoids." (PMID 28423498, 2017). "We next determined the relationship between PIAS3 and Smurf2 in the control of the malignant behavior of breast cancer cells." (PMID 28423498, 2017). "Together, these data suggest that PIAS3 acts via sumoylation of Smurf2 to inhibit the invasive behavior of breast cancer cell-derived organoids." (PMID 28423498, 2017). "We first assessed the role of endogenous Smurf2 in regulating the invasive growth of three-dimensional MDA-MB-231 breast cancer cell-derived organoids using RNA interference (RNAi)." (PMID 28423498, 2017). "By contrast, expression of Smuf2CA promoted the invasive growth of MDA-MB-231 cell-derived organoids in the absence or presence TGFβ, suggesting that the ubiquitin E3 ligase activity is critical for Smurf2 to suppress breast cancer-organoid invasive behavior." (PMID 28423498, 2017). "Together, these data suggest that endogenous Smurf2 suppresses the aggressive behavior of breast cancer-derived organoids." (PMID 28423498, 2017). "Collectively, our data suggest that the E3 ubiquitin ligase activity of Smurf2 is required for sumoylated Smurf2 to suppress the invasive growth of breast cancer-derived organoids." (PMID 28423498, 2017). "In complementary studies, expression of Smurf2 suppressed the ability of TGFβ to promote the invasive growth of three-dimensional breast cancer-cell derived organoids." (PMID 28423498, 2017). "To identify the mechanism for this anti-proliferation effect, we investigated the cell cycle distribution of breast cancer cells after silencing Smurf2 expression in MCF-7 and MDA-MB-231." (PMID 25191523, 2014). "But few studies have been performed to determine the significance of USP25 in tumor metastasis; SMURF2 is known to suppress tumor angiogenesis and metastasis, However, others reported that SMURF2 promoted metastasis in breast cancer cells." (PMID 24997798, 2014). "Collectively, these results imply that silencing of Smurf2 decreases the invasive properties of breast cancer cells." (PMID 25191523, 2014). "The present study provides the first evidence that silencing Smurf2 using synthetic siRNAs can regulate the tumorigenic properties of human breast cancer cells in a CNKSR2 dependent manner." (PMID 25191523, 2014). "Our finding that miR-15/16 and miR-128 are involved in Smurf2 downregulation in TNBC provides a new pathway to the miRNA-mediated biological processes in breast cancer." (PMID 24485087, 2014). "In order to explore the role of Smurf2 in carcinogenesis, we first screened for Smurf2 expression in different cancer cell lines by western blot and observed an elevated expression of Smurf2 in MDA-MB-231 breast cancer cell line compared to others." (PMID 25191523, 2014).